MYC (MYC proto-oncogene, bHLH transcription factor)
Diseases named in the same sentence as MYC in open-access papers (continued):
Sharing a sentence is not in itself a finding about the gene and the disease.
multiple myeloma (continued). "Meanwhile, we tested the generalization ability of the HACF model on two known super-enhancers (SE) located within chromosome 22 which were reported to be related with MYC oncogene in multiple myeloma." (PMID 30959806, 2019). "Several studies positively correlated miR-17-92 expression to MYC up-regulation during myeloma evolution, highlighting its tumor-promoting role." (PMID 31052608, 2019). "Our finding is consistent with previous studies in hematological disease models of multiple myeloma (MYC-dependent) and acute myeloid leukemia, where it was demonstrated that BET inhibition produces a potent anti-proliferative effect." (PMID 31288832, 2019). "GSEA identified overexpression of ribosomal genes, oxidative phosphorylation and respiratory electron transport chain, and MYC-regulated genes, including MYC itself, in t(IgL) myeloma." (PMID 31015454, 2019). "In multiple myeloma (MM), characterized by dysregulation of multiple factors due in large part to gene rearrangements and translocations of MYC, BRD4 was found to be enriched at IgH (immune heavy chain) enhancers rearranged at the MYC locus." (PMID 30906568, 2019). "JQ1 displacement of BRD4 from the MYC promoter/enhancer also led to suppression of MYC-driven malignancies, such as multiple myeloma and acute myeloid leukemia." (PMID 31824865, 2019). "Focal Copy number alteration (CNA) were enriched in the same regions where MYC translocation breakpoints occurred and this was particularly prevalent in MYC-translocated myeloma." (PMID 31015454, 2019). "Significant efforts have yielded a mouse model of myeloma driven by AID-dependent MYC expression, and a humanized mouse capable of sustaining the human immune system including myeloma." (PMID 31231360, 2019). "In AML with mutations in NPM1 (encoding nucleophosmin), I-BET151 abrogates the HOX-independent transcription program, and represses the MYC-dependent program in myeloma, leading to strong antiproliferative effect in vitro and in vivo." (PMID 30906568, 2019). "As a result, BRD4 inhibitors and degraders are currently being investigated as a method of downregulating MYC expression and inhibiting myeloma cell proliferation." (PMID 31231360, 2019). "In line with this, combination of AI-10-104 and lenalidomide downregulated the myeloma oncogenes MYC and IRF4." (PMID 30760870, 2019). "MYC structural variants are sometimes present in MGUS, present in ~35% of NDMM, and even more common in RRMM and myeloma cell lines." (PMID 31231360, 2019). "MYC translocation breakpoints and CNA overlapped several regions of chromatin accessibility in myeloma cell lines that coincide with known enhancers as well as insulator elements that delineate MYC and PVT1 promoter-enhancer interactions." (PMID 31015454, 2019). "MYC aberrant expression occurs in the majority of myeloma cases through amplification, translocation, or transcriptional dysregulation." (PMID 31231360, 2019). "The one exception is those myelomas with loss-of-function mutations in the MYC binding partner MAX, which express MYC at substantially lower levels." (PMID 31015454, 2019). "Here we provide evidence implying that Prevotella heparinolytica promotes the differentiation of Th17 cells colonizing the gut and migrating to the bone marrow (BM) of transgenic Vk*MYC mice, where they favor progression of multiple myeloma (MM)." (PMID 30510245, 2018). "Numerous studies have shown that c-MYC is essential for multiple myeloma cell survival and that IRF4 regulates its expression." (PMID 29346274, 2018). "To further validate the concept of synergistic anti-myeloma activity of MYC inhibition with bortezomib treatment in our experimental setting, we tested the combination of known MYC inhibitor JQ1 with bortezomib." (PMID 29472861, 2018). "Overall this data supports the usefulness of MYC inhibitory compounds with bortezomib for enhancing anti-myeloma efficacy." (PMID 29472861, 2018).
multiple myeloma (continued). "The decrease in cell viability and MYC protein levels in L363 multiple myeloma (MM) cells and other MM cells was sustained over the entirety of the 72-h time course." (PMID 30315240, 2018). "MMSET induces multiple myeloma cell growth through silencing of miR-126* and the subsequent overexpression of c-MYC, a target of miR-126*." (PMID 29796186, 2018). "In this context, the Vk*MYC transgenic mouse with spontaneously occurring myeloma tumors has been suggested as an alternative model to predict single-agent drug activity." (PMID 29029544, 2017). "MMC samples from high-risk CD-score patients are also significantly enriched in genes related to MYC target genes and the myeloma CD1 molecular subgroup." (PMID 29228738, 2017). "We investigated the immunological relevance of different models of myeloma utilizing the Vk*MYC mouse and compared those findings to our analysis of T cells in human MM." (PMID 27599546, 2016). "MYC is one of the most highly amplified and frequently translocated oncogene among a variety of human cancers, such as, multiple myeloma." (PMID 26894970, 2016). "In another study, treatment of c-MYC-expressing myeloma cells with the 10058-F4 compound, an inhibitor of MYC-MAX heterodimerization, resulted in rapid apoptosis, suggesting that there is an addiction to c-MYC for survival in these cancer cells." (PMID 27875549, 2016). "Abnormal activity of a number of transcription factors has been implicated in multiple myeloma development, including NF-κB, MAF, MYC, and interferon regulatory factor 4 (IRF4)." (PMID 26731516, 2016). "The Vk*MYC transgenic and transplant mouse models of multiple myeloma (MM) are well established as a research tool for anti-myeloma drug discovery." (PMID 27599546, 2016). "We found that in myeloma cell lines, MYC gene amplifications were common and correlated with MYC mRNA and protein." (PMID 26087190, 2015). "We found higher MYC mRNA levels in myeloma cell lines than in primary cells; although the range was approximately the same in these two groups." (PMID 26087190, 2015). "Sensitivity of myeloma cell lines to the MYC inhibitor 10058-F4 correlated with MYC expression, supporting that the activity of 10058-F4 was through specific inhibition of MYC." (PMID 26087190, 2015). "We have earlier shown that MYC expression was important for in vitro survival of myeloma cells using different approaches for targeting MYC." (PMID 26087190, 2015). "That finding supports that MYC is important for myeloma cell survival and that the inhibitor specifically targets MYC." (PMID 26087190, 2015). "These new insights into the mechanisms of selective inhibition of oncogenic drivers provide critical information for cancers with increased MYC expression including multiple myeloma, Burkitt’s lymphoma, acute myeloid leukemia, and acute lymphoblastic leukemia." (PMID 26569311, 2015). "Next, we measured MYC gene copy numbers in all 11 myeloma cell lines using PCR with primers for exon 3 and correlated the copy numbers with MYC mRNA, as well as with protein levels." (PMID 26087190, 2015). "Elevated levels of MYC in primary myeloma cells have been reported to arise from complex genetic aberrations and are more common than previously thought." (PMID 26087190, 2015). "We went on to investigate the variation in MYC gene copy numbers in myeloma patient samples by the same method as applied for cell lines." (PMID 26087190, 2015). "Inhibition of the BRD4 bromodomains with JQ1 downregulates MYC mRNA transcription and leads to G1 cell cycle arrest in diverse tumor types, such as multiple myeloma." (PMID 26284497, 2015). "Overexpression of HEXIM1 leads to limited availability of active P-TEFb as a result of sustained BET inhibition in myeloma cells having a significant impact on the transcription of a large number of genes, including oncogenic MYC." (PMID 25989842, 2015).
multiple myeloma (continued). "We have earlier shown that the small molecule MYC inhibitor 10058-F4 induces apoptosis in myeloma cell lines and primary cells." (PMID 26087190, 2015). "In particular, for multiple myeloma it is estimated that nearly half of cases carry a MYC rearrangement and that most of these reposition MYC near a super-enhancer." (PMID 26569311, 2015). "The results thus indicate that the main determinant of elevated MYC expression in myeloma cell lines is amplification of the MYC gene." (PMID 26087190, 2015). "The most important data presented here is that there was a positive correlation between MYC expression and sensitivity to the MYC activity inhibitor, 10058-F4, in myeloma cell lines." (PMID 26087190, 2015). "Translocations of c-MYC are common in multiple myeloma and the MYC activation signature is observed in a majority of MM patient samples." (PMID 25188243, 2014). "The JQ1 altered transcriptomic profile of medulloblastoma cells was heavily enriched for c-MYC-dependent gene signatures consistent with recent reports in multiple myeloma and AML." (PMID 24796395, 2014). "Using high resolution tiling arrays around the MYC locus, it was found that rearrangements of MYC are also common in newly diagnose myeloma and most of these rearrangements affect enhancers and superenhancers of MYC causing an increase in MYC expression." (PMID 25101266, 2014). "As myeloma cells are frequently dependent on MYC for cell growth, the reduction in MYC levels in response to EZH2i likely contributes to observed decrease in proliferation of MMSET-overexpressing cells." (PMID 25188243, 2014). "More importantly, super-enhancers also have been identified in oncogenes, such as MYC, in multiple myeloma (MM) cells, and JQ1-mediated BRD4 inhibition causes MYC downregulation." (PMID 24576043, 2014). "Additional genetic aberrations include c-MYC rearrangements which occur in 15% of newly diagnosed MM, 40% of advanced MM tumors and almost 90% of human myeloma cell lines (HMCLs), indicating that c-MYC overexpression is a marker of MM progression." (PMID 24327604, 2013). "E2F signatures were previously observed to be significantly down-regulated upon treatment with another BET inhibitor in multiple myeloma cell lines containing various activating genetic lesions at the MYC locus." (PMID 24009722, 2013). "In both human myeloma cell lines (HMCLs), RPMI-8226 and MM1S, inhibition of MYC protein expression by MYCi975 was associated with decreased MCT1 expression and a compensatory increase of MCT4 further supporting the association of MCT1 in the pathogenesis of MM." (PMID 39948621, 2025). "MYC has long been appreciated as an important oncogene in multiple myeloma, whereas scRNA-seq studies have implicated LAMP5 to be a novel overexpressed gene in multiple myeloma." (PMID 39699274, 2025). "This activity of TAZ in multiple myeloma is likely due, at least in part, to down-regulation of MYC and induction of miR-224, albeit through unknown mechanisms." (PMID 40440076, 2025). "As only a subset of myeloma cells secretes CXCL7, the potential association between CXCL7 and MYC expression may be diluted in the broader plasma cell RNA-seq data." (PMID 39915476, 2025). "Furthermore, combination of dasatinib and bortezomib in multiple myeloma cells was also identified as synergistic and MYC was identified as the top downregulated gene." (PMID 41025936, 2025). "In MYC-translocated multiple myeloma, ACC1 exhibits abnormal overexpression." (PMID 41169354, 2025). "Indeed, JQ1 has been shown to be effective in reducing MYC-driven transcriptional programs in multiple myeloma, leading to tumor regression." (PMID 41323280, 2025).
multiple myeloma (continued). "Moreover, in 2018, a novel inhibitor, 7594-0035 was reported to specifically target MYC indicated for the treatment of refractory multiple myeloma." (PMID 38390324, 2024). "Multiple myeloma (MM) is a heterogeneous disease characterized by frequent MYC translocations." (PMID 38714690, 2024). "Transplanted Vk*MYC myeloma cells expanded in the bone marrow and secreted IgG2b as M-protein." (PMID 39474418, 2024). "This study aimed to investigate whether cDC1 contributes protectively or pathogenically to myeloma progression in a Vk*MYC myeloma mouse model." (PMID 39474418, 2024). "Similarly to what observed in MM, in particular in hyperdiploid cases, large trisomies in the Vk*MYC myeloma tended to be acquired within the same time window in 8/10 (80%) cases where this analysis was possible." (PMID 38714690, 2024). "Vk*MYC MM cell lines Vk12598 and Vk12653 have been extensively used for myeloma research." (PMID 38714690, 2024). "Importantly, among the upregulated genes, there were several genes encoding established pro-survival and anti-apoptotic factors in myeloma, including MYC, IRF4, NFKB1/2, BCL2, and BCL2L1." (PMID 38911853, 2024). "Because monoclonal gammopathy and multiple myeloma develop at different ages in Vκ*-MYC (as in humans), mice were paired according to age, baseline total, and monoclonal IgG concentrations, and one of each pair was either treated with recombinant C3d or injected with PBS, that is left untreated." (PMID 39693340, 2024). "Similarly, in multiple myeloma cells, the reduction of MYC levels induced by FGF/FGFR inhibition triggers oxidative stress, DNA damage and apoptosis." (PMID 39031286, 2024). "The Vk*MYC mouse spontaneously develops monoclonal gammopathy and multiple myeloma." (PMID 39693340, 2024). "To test whether cDC1 supports or inhibits the progression of myeloma, we used a Vk*MYC myeloma mouse model that can be used to monitor the tumor based on CD155 and IgG2b expression, and the XCR1-DTR mouse line that can inductively deplete cDC1 in the body." (PMID 39474418, 2024). "Therefore, we used cell lines derived from multiple myeloma (MM), a malignant plasma cell disorder that is highly dependent on MYC expression." (PMID 38067212, 2023). "Additionally, while the MYC family of oncogenes regulates the expression of DHODH, the key enzymes in de novo pyrimidine synthesis, DHODH inhibitors downregulate c-MYC in melanoma, myeloma, and lymphoma cells." (PMID 36814599, 2023). "IRF4 is also a key regulator of multiple myeloma and directly activates MYC in myeloma cells." (PMID 37198323, 2023). "MYC is one of the key genes in the pathogenesis of multiple myeloma." (PMID 37198323, 2023). "In multiple myeloma (MM), compound 1 could effectively down-regulate MYC transcription due to its BET inhibitory activity, contributing to an anti-proliferative effect in a time- and dose-dependent manner." (PMID 37142850, 2023). "A targeted proteomic approach using a mass cytometry panel of myeloma response markers after a 24-h exposure to ProRS inhibitors supports and extends the observed changes in the protein abundance of MYC, MCL-1 and SDC1." (PMID 36631435, 2023). "Interestingly, c-MYC expression is increased in myeloma cells in relation to MGUS thus suggesting it to be the key player in MGUS to MM transition." (PMID 35092513, 2022). "In addition, microhomology-mediated recurrent MYC and other complex gene rearrangements have been reported in myeloma." (PMID 36011278, 2022). "MYC is a multifunctional oncogenic transcription factor that affects various cell biological processes, including cell proliferation, apoptosis, and DNA damage in various cancerous diseases, including myeloma." (PMID 35328342, 2022). "In addition, previous studies have reported that MYC negatively regulates the expression of miR-34a-5p in multiple myeloma, and YY1 levels are inversely related to miR-155 in atherogenesis." (PMID 36212136, 2022).
multiple myeloma (continued). "Human MYC gene is highly expressed in melanoma, multiple myeloma, and nasopharyngeal carcinoma." (PMID 35441564, 2022). "We recently showed that KDM5A upregulates MYC target genes in multiple myeloma cells." (PMID 35805040, 2022). "Diphtheria-toxin mediated abrogation of tissue-resident CD169+ macrophages in CD169-DTR mice, intratibially injected with myeloma cells from a syngeneic Vk*MYC mouse model, resulted in reduced dissemination of myeloma cells into the blood circulation and to the contralateral tibial bone." (PMID 35847862, 2022). "Indeed, in the short term, we observed increased c-MYC protein in multiple myeloma cells in the presence of proteasome inhibitors." (PMID 36846090, 2022). "MYC and RAS gene mutations are other common findings in multiple myeloma." (PMID 35092513, 2022). "Our results indicate that proteasome inhibitors are potent antagonists of the c-MYC regulon, highlight the transcriptional dynamics between gene activators and repressors in multiple myeloma, and open potential avenues for personalized treatment options involving epigenetic modifiers." (PMID 36846090, 2022). "In addition, TCH-165-induced clearance of MYC in various other multiple myeloma cells, including L363 and H929." (PMID 35625675, 2022). "Indeed, MCL1 inhibition is currently in early clinical testing for multiple myeloma and MYC positive diffuse large B-cell lymphoma (DLBCL) with promising results (Clinicaltrails.gov, NCT02992483)." (PMID 34654952, 2022). "To examine whether OTUB1 expression has a physiological impact on c-MYC-addicted cancers, we analyzed its expression in multiple myeloma." (PMID 35159073, 2022). "ChIP-seq assays showed that acetylation of H3K27 at cell cycle/mitochondrial gene promoters and super-enhancers of genes relevant for multiple myeloma biology (c-MYC, BCL-XL, CCND2, IRF4, MCL1, PIM1, PRDM1, and XBP1) was mildly increased in HDAC3 knockdown cells compared with nonsilencing cells." (PMID 36846090, 2022). "Thus, the Vκ*MYC model provides a unique opportunity to assess the molecular profiles of malignant cells from the earliest stages of myeloma, prior to serological detection of disease, which is typically not feasible in human studies." (PMID 34732728, 2021). "Additionally, leflunomide, an agent approved for the treatment of the rheumatoid arthritis, also exhibits anti-myeloma activity through the downregulation of MYC protein in preclinical studies." (PMID 33562668, 2021). "Moreover, overexpression of MYC protein is a characteristic of progression and poor prognosis in multiple myeloma." (PMID 34116677, 2021). "IRF4 sustains the expression of MYC, another important myeloma oncogene." (PMID 34834536, 2021). "Although the hypothesis-generating portion of our study was performed using a mouse model of myeloma, the extension of our findings to myeloma patients further supports that the Vκ*MYC model is highly recapitulative of myeloma pathogenesis." (PMID 34732728, 2021). "We also demonstrated the clinical relevance in myeloma patients of a shared transcriptional program identified from analysis of Vκ*MYC tumours using publicly available human single-cell and bulk gene expression data sets and showed that targeting this program has anti-MM activity." (PMID 34732728, 2021). "In addition, high basal MYC and HIF1α levels were observed in all multiple myeloma (MM) cell lines and primary MM cells where MYC collaborates with HIF1α to trigger VEGF production and induction of MM angiogenesis." (PMID 33572152, 2021). "Similarly, the benzofuran derivative D089 has been reported to inhibit MYC transcription and to interfere with the survival of multiple myeloma cells through the direct binding to MYC G4." (PMID 34073075, 2021). "The authors found that MYC levels were downregulated in two myeloma cell lines, which suggested that MYC itself could be a pharmacodynamic (PD) marker of BET inhibition, although its usefulness would be limited to hematologic tumors." (PMID 35582389, 2021).